CD4 (CD4 molecule)
Diseases named in the same sentence as CD4 in open-access papers (continued):
Sharing a sentence is not in itself a finding about the gene and the disease.
tuberculosis (continued). "In humans, the importance of CD4+ T cell response is supported by the dramatically increased risk of active tuberculosis with the co-infection of human immunodeficiency virus (HIV), which reduces the number of CD4+ T cells in patients." (PMID 28066410, 2016). "Incident Rate and Risk Factors for Development of Incident Active Tuberculosis Disease in HIV-Infected Persons Using A Composite Risk Factor of High HIV Viral Load, Low CD4 Cell Count and IGRA Positivity (n = 772)." (PMID 26280669, 2015). "CD4+ T cell expression of IL-10 is an important mechanism controlling immunity to tuberculosis (TB)." (PMID 26417443, 2015). "Overtime infection leads to severe depletion of CD4 T-lymphocytes (T-cells) resulting in opportunistic infections like tuberculosis (TB), fungal, viral, protozoal and neoplastic diseases and ultimately death." (PMID 25617150, 2015). "Anti-TPO antibody titers, baseline CD4 counts, and history of tuberculosis were the best predictors of subclinical hypothyroidism in HIV infected patients in our study." (PMID 26798547, 2015). "In 2013, WHO guidelines recommended expanding ART eligibility to all HIV-positive persons with CD4+ counts <500 and persons with CD4>500 who have tuberculosis or hepatitis B, pregnant or breastfeeding women, and persons in serodiscordant partnerships." (PMID 26632823, 2015). "Studies have demonstrated that in HIV-infected patients with active tuberculosis, the frequency of cavitary lung lesions is directly proportional to the number of peripheral blood CD4 T cells at the time of TB diagnosis." (PMID 26018190, 2015). "On the other hand, patients who were much older and had lower CD4 cell count were more liable for concomitant opportunistic infection (cytomegalovirus, toxoplasmosis, pneumocystis pneumonia, or tuberculosis)." (PMID 26207639, 2015). "The CD4/CD8 lymphocyte ratio in pleural effusion induced by tuberculosis is reported to be 3.1±1.1 (mean ± standard deviation)." (PMID 26271927, 2015). "CD4 nadir, time under viral suppression, gender, tuberculosis, and hepatitis C coinfection were included in the multivariate analysis model." (PMID 26355305, 2015). "This group also found that Tregs from tuberculosis patients not only suppress IFN-γ production but also inhibit IL-10 production by CD4+ T cells." (PMID 25969837, 2015). "Patients with more severe immunodeficiency (lower CD4 count) at disease onset and history of tuberculosis were more likely to have subclinical hypothyroidism later in life." (PMID 26798547, 2015). "The same trends were observed in which those co-infected with tuberculosis (OR = 2.43), those with CD4 count < 200 cells/mm (OR = 1.32) and those having HIV less than 10 years (OR = 1.45) have higher odds in getting IPIs in HIV-infected inmates." (PMID 26511347, 2015). "Among HIV-infected individuals with CD4 less than 200 cells/mm3, tuberculosis often has an atypical presentation, is more likely to be disseminated and is diagnostically challenging." (PMID 26176604, 2015). "IFN-γ, mainly produced by CD4+ T cells, plays a critical role in resistance to tuberculosis and is necessary for host survival and optimal long-term protection against M. tuberculosis." (PMID 26018190, 2015). "This is in accordance with previous studies on the tuberculosis-specific IGRA showing impaired test performance in individuals with reduced CD4+ T cell counts." (PMID 26322514, 2015). "Current results from our group indicate that a higher percentage of CD4+ cells express Notch1 in patients who are clinically cured of tuberculosis, a condition that is characterized by increased IFN-γ and IL-10." (PMID 26495323, 2015). "Depletion of T-lymphocytes in general and CD4+ cells in particular also occurs in patients with tuberculosis (TB)." (PMID 26520395, 2015).
tuberculosis (continued). "This study followed up all people at least 18 years of age with an HIV infection in Shenzhen from December 2003 to February 2014 and estimated the effects of ART on mortality, tuberculosis and CD4 cell counts by unweighted and weighted models." (PMID 26213959, 2015). "Among HIV-infected tuberculosis suspects, lower CD4 count, hemoglobin ≤8.5 g/dL, and the presence of microbiologically confirmed pulmonary tuberculosis were associated with increased adjusted odds of mycobacteremia." (PMID 25582793, 2015). "Emerging evidence indicates a role for IL-17 and the CD4+ subset T helper 17 (TH17) cells in immune responses to tuberculosis." (PMID 26835156, 2015). "It is estimated that IRIS occurs in at least 10% of patients with HIV who started on ART concomitantly with tuberculosis treatment and it is seen commonly in patients with low numbers of CD4 cells." (PMID 25478257, 2014). "The vigorous restitution of CD4 cell counts within the first six months of therapy was accompanied by the occurrence of IRIS in some patients, of which tuberculosis was the commonest reported cause followed by herpes zoster and cerebral toxoplasmosis." (PMID 25340766, 2014). "We noticed a significant inverse relationship of CD4 count with respect to the frequency of Tregs and FoxP3 expression, making these subjects more vulnerable to active tuberculosis in this immune-compromised state." (PMID 25198707, 2014). "Tuberculosis incidence rates decreased with increasing CD4 count at study entry and duration on combination antiretroviral therapy." (PMID 25393281, 2014). "Among 119 first episodes of confirmed tuberculosis, 68 were in patients with CD4 counts less than 200 cells per mm3." (PMID 25474641, 2014). "The addition of urine LAM to existing screening strategies would be relatively inexpensive, and the rapid urine LAM test has been reported to be cost-effective when used to diagnose HIV-infected adults with CD4 < 100/mm3 and symptoms of tuberculosis." (PMID 24571362, 2014). "First, CD4 count is related to the severity and clinical presentation of tuberculosis in co-infection, extrapulmonary and disseminated as observed in our study." (PMID 25066655, 2014). "Multiple CD4+ Treg-cell marker expressing subsets have been demonstrated in patients with tuberculosis and after vaccination with MVA85A and BCG." (PMID 24714620, 2014). "The mean final CD4+ count at the end of tuberculosis therapy was 253.8 (42.4) cells/mm3, and significantly higher (p = 0.03) than baseline." (PMID 25406657, 2014). "While continued scale-up of antiretroviral therapy programs is important, multiple studies have suggested that tuberculosis incidence among persons on antiretroviral therapy and with high CD4 counts still exceeds incidence in the HIV-negative population." (PMID 24937804, 2014). "Higher mortality in PLHIV reporting a current cough without bacteriological confirmation of tuberculosis was identified for those with a CD4 cell count <200, abnormal chest X-ray, anemia and empirical treatment for tuberculosis." (PMID 24679187, 2014). "Studies with tuberculosis patients and in animal models have indicated indispensable roles of both CD4+ and CD8+ T cells in host resistance against M. tuberculosis infection." (PMID 24711459, 2014). "Using these epitopes, we made an ESAT-6-specific MHC class II tetramer to detect the kinetics of tuberculosis-specific CD4+ lymphocytes." (PMID 24741623, 2014). "Seven of the 8 fatalities were HIV-infected with a median CD4 count of 87 cells/mm3 and 5 of the 7 were co-infected with tuberculosis." (PMID 24695805, 2014). "In the LCMV model, PD-1 expression on CD8+ lymphocytes is a marker of cell exhaustion; however, in the tuberculosis model, CD4+ lymphocytes that express PD-1 have proliferative potential, suggesting that these are effector CD4 cells." (PMID 24741623, 2014).
tuberculosis (continued). "HIV-infected adults with CD4+ T cell count ≤200/mm3 received standard 6-month tuberculosis treatment and antiretroviral therapy including a daily-dose of 600 mg of efavirenz, irrespective of their body weight." (PMID 24608960, 2014). "Interventions to prevent tuberculosis in this population should address geographical, socioeconomic and individual factors such as low CD4 counts and prior history of tuberculosis." (PMID 25393281, 2014). "Anti-retroviral therapy reconstitutes the number and function of CD4+ T-cells and most patients manifest clinical improvement of signs and symptoms of opportunistic co-infections including tuberculosis (TB)." (PMID 25275318, 2014). "Plasmid DNA vaccination is a powerful tool to identify protective antigens of tuberculosis and to identify immunodominant CD4+ and particularly CD8+ T-cell epitopes." (PMID 25071781, 2014). "Being female and having a low CD4 count, high HIV-1 RNA load, low body mass index and smear-positive pulmonary tuberculosis were independently associated with tuberculosis-IRIS." (PMID 24367678, 2013). "In a community tracking survey of patients LTFU in Ethiopia, nearly half of patients LTFU died, most deaths occurred during the first 6 months of loss, and the mortality was particularly higher in those patients with lower CD4 cell counts or tuberculosis." (PMID 24028937, 2013). "National guidelines on timing of ART initiation for tuberculosis patients were that those with CD4 counts less than 50 cells/mm3 should be initiated within 2 weeks, and those with higher CD4 counts should be started within 2 months." (PMID 24312317, 2013). "Time course analyses of CD4+ T cells from selected tuberculosis patients revealed markedly increased miRNA candidate expression during the first months of chemotherapy (data not shown)." (PMID 23613882, 2013). "In the South African Starting Antiretroviral Therapy at Three Points in Tuberculosis Therapy (SAPIT) randomized trial, receipt of concurrent ART was associated with survival benefit among those with CD4 cell counts of <200 cells/μl and 200 to 500 cells/μl." (PMID 24295487, 2013). "In active tuberculosis, compared with latent tuberculosis infection, a higher percentage of CD4+ cells secreting IFN-γ-only or TNF-α-only in response to PPD and RD1-peptides were TEFF." (PMID 23966657, 2013). "In a previous study of sixteen IRIS cases, among which only 2 (12.5%) manifested as tuberculosis, CD4+ T cell activation was demonstrated to be a feature common to the diverse manifestations of IRIS." (PMID 23688318, 2013). "We determined the expression profile of 29 selected miRNAs in CD4+ T cells from tuberculosis patients and contacts with latent M. tuberculosis infection (LTBI)." (PMID 23613882, 2013). "This rendered a common cause of decreased miR-21, miR-26a, miR-29a, and miR-142-3p of CD4+ T cells from tuberculosis patients likely." (PMID 23613882, 2013). "Although CD4+ T cells have been shown to be of crucial importance in resistance to infection and/or disease, the role of the various CD4+ T cell subsets remains to be clarified, especially in extra-pulmonary forms of tuberculosis in an high – endemic setting." (PMID 23544075, 2013). "All M. tuberculosis-specific CD4+ subsets, with the exception of IL-2-only cells, switched from central to effector memory phenotype in active tuberculosis vs latent tuberculosis infection, accompanied by a reduction in IL-7 receptor α (CD127) expression." (PMID 23966657, 2013). "Diagnosis of tuberculosis, being homeless, lower CD4 count, longer duration of pre-ART care, belonging to a disadvantaged community, being widowed, and not living near a town were associated with delayed ART initiation." (PMID 24288689, 2013). "Vitamin D deficiency is very common among hospitalized adult tuberculosis patients in Uganda especially in patients with hypoalbuminemia, anemia, HIV co-infected patients with CD4 count <200cells/mm3 and hypocalcemia corrected for serum albumin levels." (PMID 23886009, 2013).
tuberculosis (continued). "Limited donors numbers included for CD4+ T-cell miRNA expression analyses prompted us to perform a follow-up case/control study in children with tuberculosis, LTBI, and PPDneg contacts." (PMID 23613882, 2013). "Our results illustrate a yet unrecognized interplay between Gr1+ cells and CD4+ T cells in tuberculosis." (PMID 24224058, 2013). "Th-17 and regulatory T cells are two other CD4+ T cell subpopulations that play a role in immunity against tuberculosis." (PMID 23675482, 2013). "Patients with CD4 count less than 200/mm3 are 9.4, 27.2, 11.1 and 8.2 times more likely to develop tuberculosis, oral candidiasis, skin fungal infections and pneumonia respectively compared to the reference category CD4 count >350/mm3." (PMID 24330921, 2013). "Early ART is also known to reduce the risk of developing tuberculosis, the leading cause of mortality in HIV infected individuals, which increases with declining CD4 counts below 500cells/ μL." (PMID 23554867, 2013). "The median CD4+ lymphocyte count at ART initiation among persons with tuberculosis in our study was 64/mm3." (PMID 24066096, 2013). "These analyses showed lower expression of miR-21, miR-26a, miR-29a, and miR-142-3p in CD4+ T cells from tuberculosis patients." (PMID 23613882, 2013). "Differentially expressed miRNAs showed decreased expression in CD4+ T cells from tuberculosis patients as compared to LTBI and PPDneg." (PMID 23613882, 2013). "Where CD4+ M. tuberculosis-specific effector-like cells were influenced by tuberculosis disease stage, the impact of HIV coinfection per se was rarely significantly associated with these changes." (PMID 23966657, 2013). "Nevertheless, IL-10 is clearly an important regulatory mechanism in tuberculosis, with the ability to modulate the different arms of CD4+ T immunity." (PMID 23544075, 2013). "Diagnosis of tuberculosis, being homeless, lower CD4 count, shorter duration of pre-ART care, belonging to a disadvantaged community, illiteracy, and age >45 years were associated with mortality." (PMID 24288689, 2013). "On the one hand, antigen-specific CD4+ T cell responses are critical for protection against tuberculosis, and Mtb has evolved many strategies that subvert and evade the host adaptive immune response." (PMID 24130562, 2013). "The median CD4-cell count was 22 per microliter (range 2–253), concurrent opportunistic infections (OI) included tuberculosis (n = 6) and cryptococcal meningitis (n = 3)." (PMID 23272255, 2012). "Since some studies contributed tuberculosis cases to CD4-stratum estimates and to estimates across all CD4 counts, the data used for the meta-analyses are not independent." (PMID 22911011, 2012). "Whenever feasible, we assessed how HIV-associated CD4+ T-cell depletion affects IGRA performance, and tried to identify differences according to tuberculosis burden settings and HIV infection status." (PMID 22403663, 2012). "In multivariate analysis, only CD4+ lymphocyte count (AOR = 2.9; 95% CI: 1.002-8.368) was found to be independently associated with tuberculosis-HIV co-infection." (PMID 22738361, 2012). "Patients diagnosed of HIV for antenatal screening or having an HIV-positive sexual partner had higher CD4 lymphocyte count than patients having tuberculosis or HIV-related symptoms." (PMID 22611389, 2012). "The interaction of HIV and tuberculosis (TB) on CD4 levels over time is complex and has been divergently reported." (PMID 22436147, 2012). "The prevalence of tuberculosis in patients with CD4 counts of less than 100 cells per μL was 26·4% (95% CI 19·3–34·5), with less than 200 cells per μL was 19·5% (95% CI 15·4–24·1), and 200 or more cells per μL was 13·3% (95% CI 8·9–18·9)." (PMID 22015305, 2012). "This has led to ART access being prioritised for those with the lowest CD4 cell counts (and patients with active tuberculosis [TB])." (PMID 22802738, 2012).
tuberculosis (continued). "The assay correctly identified more than two-thirds of tuberculosis cases with CD4 counts less than 50 cells per μL and about half of cases with counts less than 100 cells per μL." (PMID 22015305, 2012). "Our results are conservative in that we also omitted several important types of health benefits and care savings: preventing tuberculosis in index patients and contacts, benefits to family members, and benefits above CD4 count of 500 cells/mm3." (PMID 22348000, 2012). "At 12 months, those with available results had higher baseline absolute CD4 and had a higher rate of tuberculosis at ART initiation." (PMID 22438965, 2012). "The importance of CD4+ and CD8+ T cells in protection against tuberculosis (TB) is well known, however, the association between changes to the T cell repertoire and disease presentation has never been analyzed." (PMID 23110186, 2012). "Patients diagnosed with tuberculosis had lower CD4 cell counts and were more likely to have advanced WHO stage of disease than were those with higher CD4 cell counts." (PMID 22015305, 2012). "IFNγ and IL-10 producing CD4+ T cell clones were first obtained in active tuberculosis patients and patients with Lyme disease." (PMID 23152883, 2012). "In particular, Cyclic-β glucans enhance the in vitro memory CD4+ T cell responses of patients suffering from hepatitis C and tuberculosis." (PMID 23166489, 2012). "Recent studies revealed that the proportion of single-positive TNF-α Mtb-specific CD4+ T cells is a new tool for the rapid diagnosis of active tuberculosis disease." (PMID 23272100, 2012). "Risk of death was also associated with a lower CD4 cell count, age ≥ 40 at diagnosis, and MDR tuberculosis." (PMID 22489253, 2012). "In the current SR, we tried to determine the impact of CD4+ T-cell counts on the sensitivity of IGRAs in HIV-infected patients with active tuberculosis disease, but the results were inconclusive." (PMID 22403663, 2012). "These patients are diagnosed of tuberculosis with low a CD4+ lymphocyte count and a high proportion of them present with extrapulmonary tuberculosis." (PMID 23316226, 2012). "In India, still 40–50% of HIV-infected patients are diagnosed of HIV when their CD4+ lymphocyte count is below 200 cells/mm3, and, in many cases, tuberculosis is the first manifestation of HIV infection." (PMID 23316226, 2012). "After adjusting for age, sex and height, low CD4 count, history of anti-tuberculosis treatment and alcohol intake remained significantly associated with HIV-SN." (PMID 23181417, 2012). "The objective of this study was to systematically review the effect of antiretroviral therapy on incident tuberculosis in developing countries across a range of CD4 cell count strata." (PMID 22911011, 2012). "It was observed that higher age, lower CD4 counts at baseline, presence of tuberculosis at any study time point and ART naive status were significantly associated with mortality." (PMID 21537095, 2011). "CD27− CD4 T cells have been identified as protective against tuberculosis via IFN-γ production, although simultaneous cytokine production potential was not assessed in these studies." (PMID 21720558, 2011). "In tuberculosis, primarily CD4+ T-cell subsets are involved in the amplification of an immune response by secreting several cytokines." (PMID 22043291, 2011). "Fifty five HIV seropositive patients were diagnosed with confirmed tuberculosis and had a CD4 T-lymphocyte count result." (PMID 21249220, 2011). "CD4+ T cell counts in HIV-positive patients with active tuberculosis ranged from 97/mm3 to 740/mm3 (mean: 384 ± 277/mm3)." (PMID 20936150, 2011). "tuberculosis CD4+ T cellresponses, infected mice and humans treated with anti-mycobacterial drugs toeliminate primary infection remain susceptible to reinfection." (PMID 21637811, 2011).